BTBD17 (BTB domain containing 17)
Synonyms: LGALS3BPL; BTBD17A; TANGO10A
Tractability: Antibody: UniProt places it where antibodies can reach, with high confidence; UniProt predicts a signal peptide or a membrane-spanning region; its Gene Ontology location is reachable by antibodies, with medium confidence.
Gene: Protein-coding gene on chromosome 17 (74,356,416 to 74,361,868, reverse strand). Ensembl gene ENSG00000204347.
Subcellular location: Secreted
Subcellular location (Human Protein Atlas): Cytosol; Predicted to be secreted
Gene Ontology:
Biological process: negative regulation of viral genome replication; response to virus
Cellular component: cytoplasm; plasma membrane; extracellular region
Genetic constraint (gnomAD): Loss-of-function variants: 26 observed, 24.22 expected, observed/expected ratio (o/e) 1.07, 90% interval 0.79 to 1.49. The synonymous counts are far from expectation, so gnomAD's model fits this gene poorly and the ratio says little. Missense variants: 630 observed, 531.22 expected, observed/expected ratio (o/e) 1.19, 90% interval 1.11 to 1.27. Synonymous variants: 341 observed, 265.85 expected, observed/expected ratio (o/e) 1.28, 90% interval 1.17 to 1.4.
Homologues: Orthologues: chimpanzee BTBD17 (99% identical), macaque BTBD17 (98% identical), guinea pig BTBD17 (94% identical), dog BTBD17 (94% identical), pig BTBD17 (94% identical), mouse Btbd17 (93% identical), rat Btbd17 (93% identical), zebrafish btbd17b (57% identical), tropical clawed frog btbd17 (57% identical), zebrafish btbd17a (56% identical), Drosophila melanogaster Tango10 (27% identical). Paralogues in human: ENC1 (17% identical), KLHL25 (17% identical).
Diseases named in the same sentence as BTBD17 in open-access papers:
BTBD17 is named in the same sentence as 1 disease in open-access papers, as found by Europe PMC text mining. Sharing a sentence is not in itself a finding about the gene and the disease. The quoted sentences say what the papers report.
cancer (2 papers, 2016 to 2025). A tumor composed of atypical neoplastic, often pleomorphic cells that invade other tissues. "Similarly, Renca cells showed dynamic expression changes of multiple genes across passages, including Btbd17, Loxl3, Raf1, and Acvrl1, which may be closely associated with signal transduction, transcriptional regulation, and cancer-related pathways." (PMID 41272245, 2025). "Most of these genes have not been previously reported in HCC, and BTBD17, MIR6089, ZNF205-AS1 and ZP1 have not previously been linked to cancer; only two genes (DAB2IP and ZNF185) have been reported in HCC." (PMID 27768594, 2016).